H3-7 (H3.7 histone (putative))
Description:
Core component of nucleosome. Nucleosomes wrap and compact DNA into chromatin, limiting DNA accessibility to the cellular machineries which require DNA as a template. Histones thereby play a central role in transcription regulation, DNA repair, DNA replication and chromosomal stability. DNA accessibility is regulated via a complex set of post-translational modifications of histones, also called histone code, and nucleosome remodeling.
Synonyms: H3-2; HIST2H3PS2; p06; H3.7
Tractability: PROTAC: UniProt records ubiquitination sites on it; ubiquitination databases record sites on it.
Gene: Protein-coding gene on chromosome 1 (143,894,544 to 143,905,977, reverse strand). Ensembl gene ENSG00000273213.
Subcellular location: Nucleus; Chromosome
Subcellular location (Human Protein Atlas): Nucleoplasm
Gene Ontology:
Molecular function: nucleosomal DNA binding; structural constituent of chromatin; DNA binding; protein heterodimerization activity
Biological process: heterochromatin formation; kinetochore assembly; mitotic metaphase chromosome alignment
Cellular component: nucleoplasm; nucleus; CENP-A containing nucleosome; kinetochore; chromosome; nucleosome
Genetic constraint (gnomAD): Loss-of-function variants: 6 observed, 6.41 expected, observed/expected ratio (o/e) 0.94, 90% interval 0.51 to 1.72. That is too few expected variants to judge how well the gene tolerates losing a copy. Missense variants: 208 observed, 189.86 expected, observed/expected ratio (o/e) 1.1, 90% interval 0.98 to 1.23. Synonymous variants: 101 observed, 86.01 expected, observed/expected ratio (o/e) 1.17, 90% interval 1 to 1.38.
Homologues: Orthologues: Drosophila melanogaster His3:CG33812 (97% identical), zebrafish si:ch1073-153i20.2 (96% identical), zebrafish si:ch211-113a14.20 (96% identical), zebrafish si:ch211-113a14.23 (96% identical), zebrafish si:ch211-113a14.27 (96% identical), zebrafish zgc:173552 (96% identical), Caenorhabditis elegans his-17 (95% identical), Caenorhabditis elegans his-2 (95% identical), Caenorhabditis elegans his-32 (95% identical), Caenorhabditis elegans his-40 (95% identical), Caenorhabditis elegans his-42 (95% identical), Caenorhabditis elegans his-45 (95% identical), and 5 more. Paralogues in human: H3C1 (97% identical), H3C10 (97% identical), H3C11 (97% identical), H3C12 (97% identical), H3C13 (97% identical), H3C14 (97% identical), H3C15 (97% identical), H3C2 (97% identical), H3C3 (97% identical), H3C4 (97% identical), H3C6 (97% identical), H3C7 (97% identical), and 8 more.
Diseases named in the same sentence as H3-7 in open-access papers:
H3-7 is named in the same sentence as 4 diseases in open-access papers, as found by Europe PMC text mining. Sharing a sentence is not in itself a finding about the gene and the disease. The quoted sentences say what the papers report.
tumor (1 paper, 2013). "RBM5 (RNA-binding motif protein 5, also named H37/LUCA-15) gene from chromosome 3p21.3 has been demonstrated to be a tumor suppressor." (PMID 23721095, 2013).
H3-7 also shares sentences with these, for which no sentence is quoted: brain tumor (1 paper); cancer (1); epithelial ovarian cancer (1).